CRP (C-reactive protein)
Diseases named in the same sentence as CRP in open-access papers (continued):
Sharing a sentence is not in itself a finding about the gene and the disease.
sarcopenia (continued). "At present, a variety of predictors have been proposed to predict outcomes after surgery, such as the C-reactive protein (CRP), procalcitonin (PCT), platelet-to-lymphocyte ratio (PLR), neutrophil to lymphocyte ratio (NLR), body mass index (BMI), sarcopenia, and albumin (ALB) levels." (PMID 33727917, 2021). "A meta-analysis reported that blood CRP levels were significantly higher among patients (mean age > 60 years) with sarcopenia compared to those without sarcopenia (standardized mean difference = 0.51; 95% CI = 0.26, 0.77)." (PMID 34836213, 2021). "We also found CRP among older Chinese population with possible sarcopenia was significantly higher than those without sarcopenia." (PMID 33661964, 2021). "There were substantial reductions in the levels of inflammation indicators such as CRP (from 6.17 μg/mL to 2.97 μg/mL) and TNF-α (from 10.24 pg/mL to 9.52 pg/mL), and this was especially pronounced in the sarcopenia group (CRP: from 6.32 μg/mL to 2.69 μg/mL; TNF-α: from 10.69 pg/mL to 9.35 pg/mL)." (PMID 33882026, 2021). "Third, other parameters that were not assessed included the CRP-to-albumin ratio, estimated glomerular filtration rate, platelet-to-lymphocyte ratio, sarcopenia, and preoperative prealbumin concentration." (PMID 31429742, 2019). "In this context, it is interesting that several clinical studies have demonstrated a link between the specific pattern of increased CRP and decreased albumin concentrations with sarcopenia, frailty and vascular and non-vascular mortality in elderly subjects." (PMID 30733685, 2018). "In addition, the association between the Hs-CRP/HDL-C ratio and sarcopenia followed a nonlinear trend." (PMID 40672942, 2025). "Furthermore, RCS analyses quantified a nonlinear dose–response relationship between CRP levels and sarcopenia statuses." (PMID 40791098, 2025). "In our study, CRP was significantly elevated in patients with sarcopenia (p = 0.035), in contrast to those without sarcopenia (3.45 vs. 2.70), and the stated elevated value of CRP could indicate the presence of chronic inflammation." (PMID 40430249, 2025). "According to dose–response analyses, CRP levels showed a nonlinear relationship with sarcopenia." (PMID 39969369, 2024). "Strong correlations were detected between sarcopenia and the EPR (r=-0.42, p<0.001), between sarcopenia and CRP (r=0.31, p=0.002), between the EPR and CRP (r=-0.39, p<0.001), between frailty and the MNA-SF score (r=-0.57, p<0.001), and between the CAT score and CRP (r=0.29, p=0.004)." (PMID 38646255, 2024). "Therefore, sarcopenia exhibited a nonlinear relation with CRP levels (P < .001) using the restricted cubic spline model." (PMID 39969369, 2024). "In a 2017 systematic review, pooled analysis of 16 cross-sectional studies showed that blood C-reactive protein (CRP) was significantly higher in people with sarcopenia than in people without sarcopenia, although there was high heterogeneity across the studies." (PMID 38279167, 2024). "A comprehensive analysis of 17 investigations encompassing 11,249 subjects (3,072 diagnosed with sarcopenia and 8,177 as controls) revealed that individuals affected by sarcopenia exhibited decidedly elevated CRP levels in comparison to their nonsarcopenic counterparts." (PMID 39502753, 2024). "However, the present study found statistically significant differences in CRP, ESR, DAS28-CRP, and DAS28-ESR between the sarcopenia group and the non-sarcopenia group, suggesting that inflammation may play a role in the development of sarcopenia." (PMID 39136015, 2024). "Additionally, sarcopenia and MDD show a direct relationship to a large extent due to the immunoinflammatory alterations they share, such as elevated levels of IL-6, CRP and TNF-α, responsible for the induction of numerous systemic changes observed in patients with sarcopenia and MDD." (PMID 39681901, 2024).
sarcopenia (continued). "Our present study is the first to have demonstrated a significantly higher CRP/albumin ratio in sarcopenia compared to no sarcopenia older adult, and the ratio could be used as one of the novel biomarkers of inflammation in sarcopenia." (PMID 37465171, 2023). "Additionally, WP did not influence CRP in individuals aged <60 or ≥60 y; with sarcopenia or prefrailty; or when the dose was <30 g/d or ≥30 g/d." (PMID 38076400, 2023). "The documented outcomes of high-protein diets, not specific to the Carnivore Diet, include reductions in C-reactive protein, the mitigation of sarcopenia in older adults, increased cholesterol levels, decreased HDL/LDL ratio, and increased probability of colon and breast cancer." (PMID 37960179, 2023). "In addition, higher CRP levels were observed in the sarcopenia group than in the non-sarcopenia group." (PMID 35570546, 2022). "In fact, a recent meta-analysis of 17 cross-sectional studies involving a total of 11,249 participants confirmed that those with sarcopenia had significantly higher CRP levels than those without, while serum IL-6 levels and TNF-α were comparable in both groups." (PMID 36291982, 2022). "While in maintenance hemodialysis patients, it is reported that CRP levels positively correlate with synthesis, degradation, and negative protein balance in muscle, in the ND-CKD population, more research is needed to elucidate the role of inflammatory markers with sarcopenia in these individuals." (PMID 35463026, 2022). "In our current study, the sarcopenia group had higher CRP levels than the non-sarcopenic group, which supported the hypothesis that systemic inflammation serves as a link between sarcopenia and MS." (PMID 34403431, 2021). "Furthermore, some circulating biomarkers of sarcopenia, such as the C-reactive protein and interleukin 6, were not considered in this study." (PMID 35083235, 2021). "Furthermore, the sarcopenic group had higher CRP and lower iron levels (ferritin) compared to those without sarcopenia (p < 0.05)." (PMID 33853546, 2021). "CRP and fibrinogen are non-specific inflammation markers; they are usually increased in oncologic patients but their significant rise in sarcopenic people can support the inflammatory substrate of sarcopenia itself." (PMID 34944975, 2021). "Patients with sarcopenia had higher C‐reactive protein (CRP) than those without sarcopenia." (PMID 31788651, 2019). "In this context, it is interesting that several clinical studies could demonstrate a link between the specific pattern of increased CRP and decreased albumin concentrations with sarcopenia, frailty, and vascular and non-vascular mortality in elderly subjects." (PMID 30715588, 2019). "Elevated values of C-reactive protein without a clinical focus of inflammation may indicate cachexia and a worse outcome, whereas changes in adipose tissue, sarcopenia and cachexia alone were not of prognostic significance." (PMID 31717736, 2019). "Sarcopenia was significantly associated with higher age, lower mean upper arm circumference, lower phase angle by BIA, lower serum levels of creatinine and hemoglobin, higher CRP, but not with differences in serum albumin, BMI or waist circumference." (PMID 30305034, 2018). "However, a recent meta-analysis of the relationship between three markers of inflammation and sarcopenia only showed a relationship with CRP but none with TNF or IL-6." (PMID 29101476, 2018). "Proinflammatory cytokines, such as IL-6 and TNF-α, induce the production of CRP in the liver, and it has not been clarified whether high CRP level directly affects sarcopenia." (PMID 29259690, 2016). "Sarcopenia was present in 128 patients (68.8%), and sarcopenic patients had significant serum lymphocyte counts and albumin levels (p = 0.002 and 0.041, respectively), and higher NLRs and CRP levels (p = 0.011 and 0.026) than non-sarcopenic patients." (PMID 27537502, 2016).
sarcopenia (continued). "Inflammatory biomarkers such as C-reactive protein (CRP), granulocyte–monocyte colony-stimulating factor (GM-CSF), interferon-γ (IFNγ), interleukins (IL-6 and IL-8), myeloperoxidase (MPO), P-selectin, and tumor necrosis factor-α (TNF-α) may naturally be elevated in cases of acute sarcopenia." (PMID 39458423, 2024). "High levels of circulating pro-inflammatory cytokines (CRP, IL-6, TNF-α, etc.)have been found to correlate with low lower handgrip, decreased appendicular muscle mass and reduced knee-extension strength, indicating that these cytokines could be potential biomarkers of sarcopenia." (PMID 36499366, 2022). "Regarding the mixed results observed in our study, CRP, but not IL-10 and TNF-α, significantly related to low physical performance, a systematic review and meta-analysis of 17 studies with 11,249 individuals also showed that only CRP, but not TNF-α and IL-6, is associated with sarcopenia." (PMID 35525916, 2022). "In male patients, those with sarcopenia were significantly older and had lower height, calf circumference, hemoglobin, albumin, and GNRI scores, as well as higher CRP levels compared with nonsarcopenic males." (PMID 41393007, 2025). "The mean CRP and ESR values were higher in the sarcopenia group at one month and at the end of the six-month follow-up when compared to no sarcopenia group and this was statistically significant." (PMID 40476129, 2025). "When comparing patients with CKD and sarcopenia with patients with CKD but without sarcopenia, the former group was characterised by elevated levels of CRP." (PMID 39126043, 2024). "Third, due to the lack of sarcopenia occurrence or severity data in the NHANES database, we were unable to evaluate the correlation of CRP levels with the clinical characteristics of sarcopenia." (PMID 39969369, 2024). "HOMA-IR and C-Reactive Protein (CRP) were significantly higher, whereas BMI and gait speed were lower in sarcopenic individuals than counterparts without sarcopenia." (PMID 34341404, 2021). "Age and C-reactive protein (CRP) levels, and Kt/V were significantly higher in patients with sarcopenia than in those without sarcopenia." (PMID 30922266, 2019). "The present study did not demonstrate the relationship of CRP levels with sarcopenia symptomology, however, the value of AUC obtained for the E-DII + CRP model (AUC = 0.754) proved that it was an acceptable discrimination of sarcopenic patients from healthy individuals." (PMID 41345186, 2025). "Third, data on inflammatory markers (eg,C-reactive protein (CRP), interleukin-6 (IL-6)) were not available while these markers mightcorrelate with the body inflammatory status and sarcopenia." (PMID 38885304, 2024). "C-reactive protein (CRP) (p = 0.011) and CRP/albumin ratio (p = 0.030) as well as IL-1β (p = 0.002), cfDNA (p < 0.001) and bilirubin levels (p = 0.002) were significantly higher in the sarcopenia group as opposed to the no sarcopenia group." (PMID 37465171, 2023). "However, zonulin, calprotectin and CRP were significantly elevated and IGF‐1 and irisin were significantly reduced in cirrhotic patients with sarcopenia, compared with non‐cirrhotic patients with and without sarcopenia." (PMID 37767786, 2023). "They found that moderate to severe disability was higher in patients with sarcopenia (48.68 vs. 31.43%, p = 0.043), patient-generated SGA ≥ 4 (39.47 vs. 17.14, p = 0.003), and high CRP levels (27.63 vs. 11.43%, p = 0.021) than in the without-to-minimal disability group." (PMID 37510827, 2023). "However, the correlation between the sarcopenia marker SMI and CRP was not significant." (PMID 37404120, 2023). "In addition, the independent relationship between sarcopenia and dietary inflammatory potential is significant among CKD patients with high levels of CRP and NLR, whereas the same phenomenon was not shown in subjects with low levels of CRP and NLR." (PMID 35634405, 2022).
Arthritis (396 papers, 2004 to 2026). Inflammation of a joint. "This study aims to investigate the association between CRP levels and all-cause mortality in Chinese arthritis patients, highlighting its implications for public health education and intervention programs." (PMID 39980916, 2025). "Our findings align with these studies, reinforcing the role of CRP as a critical predictor of mortality risk in arthritis patients." (PMID 39980916, 2025). "This study demonstrates a significant association between elevated CRP levels and increased all-cause mortality in arthritis patients, emphasizing the importance of systemic inflammation as a public health concern." (PMID 39980916, 2025). "By leveraging the CHARLS database, this study aims to examine the association between CRP levels and all-cause mortality in arthritis patients." (PMID 39980916, 2025). "The association between elevated CRP levels and increased all-cause mortality in arthritis patients has significant implications for public health education and promotion." (PMID 39980916, 2025). "Fever (p=0.01), arthralgia/arthritis (p=0.01), and high CRP (p=0.04) were significantly associated with vasculitis." (PMID 40385871, 2025). "Elevated CRP levels are strongly associated with increased all-cause mortality in arthritis patients, underscoring the importance of integrating CRP monitoring into public health education and promotion strategies." (PMID 39980916, 2025). "Future research should aim to validate these findings in diverse populations and explore the causal pathways linking CRP levels to mortality risk in arthritis patients." (PMID 39980916, 2025). "Kaplan–Meier survival curves further confirmed that arthritis patients with CRP levels ≥3 mg/L faced a markedly higher mortality risk." (PMID 39980916, 2025). "Arthritis patients with CRP levels ≥3 mg/L demonstrated a markedly higher risk of mortality over the 10-year follow-up period compared to those with lower CRP levels." (PMID 39980916, 2025). "Cox proportional hazards regression analysis demonstrated a significant association between CRP levels and all-cause mortality risk among arthritis patients across all three models." (PMID 39980916, 2025). "When compared to a healthy control group of individuals with arthritis, this review provides valuable insights into the diagnostic and prognostic use of uric acid, CRP, ADAs, and RF." (PMID 38699124, 2024). "According to joint involvement, the presence of arthritis was significantly associated with high CRP, low albumin, and high CAR (p < 0.05)." (PMID 39050391, 2024). "Higher CRP can be associated with chronic inflammatory diseases such as arthritis, which on the previous TILDA main analysis was more common in PF2 participants (37.4% vs. 30.0%, p = 0.005)." (PMID 35314597, 2022). "A wide variety of conditions like arthritis, encephalopathy and Sjogren’s syndrome are associated with the disease, besides the increased C-Reactive Protein (CRP) and Erythrocyte Sedimentation Rate (ESR) levels." (PMID 35650613, 2022). "The increased serum COMP and CRP levels in response to the underlying inflammatory condition is used as a biomarker for arthritis, including OA." (PMID 33776996, 2021). "Some patients reported mild to moderate arthralgias and arthritis, but a causal relationship with the paquinimod-induced increased CRP levels is difficult to prove in an open-label study, as joint inflammation is part of the SSc spectrum." (PMID 34330322, 2021). "Boswellia is thought to exert its beneficial effects on arthritis by improving the knee joint gap, reducing osteophytes, and attenuating inflammatory mediators, such as C-reactive protein and hyaluronic acid, associated with knee OA." (PMID 33126603, 2020). "In a previous study, arthritis on radiological examination was associated with the cutaneous subset, CRP >10 mg/l, and disease duration." (PMID 33163868, 2020).
Arthritis (continued). "Further, in a CIA rhesus monkey model, Atrosab administration resulted in reduced acute-phase C-reactive protein (CRP) and IL-6 levels in serum, prevented body weight loss, delayed the onset of arthritic symptoms and improved the clinical arthritis score." (PMID 32528961, 2020). "Attacks consist of fever, serositis, arthritis and high levels of inflammatory reactants: C-reactive protein, erythrocyte sedimentation rate, serum amyloid A associated with leucocytosis and neutrophilia." (PMID 31941537, 2020). "Elevated levels of ESR and CRP are common in systemic sarcoidosis patients, specifically in sarcoidosis-associated arthritis and erythema nodosum compared to other clinical presentations." (PMID 30411142, 2019). "In summary, our results indicate that CRP concentration mediates the association between well-being and arthritis risk (after taking demographic and health behavior differences into account)." (PMID 28604559, 2017). "Mediation analysis revealed that the indirect effect of CASP-19 intercept on arthritis risk via CRP intercept was significant with 1 unit increase in CASP-19 associated with a 0.004% reduction in arthritis risk (p < .001)." (PMID 28604559, 2017). "PRL infusion in AIA was associated with reduced serum levels of C-reactive protein (CRP) and TNFα, two biomarkers of systemic inflammation in arthritis." (PMID 28506283, 2017). "The mediation effect in our study was small due to the fact that CRP concentration at wave 2 was only weakly related to arthritis risk." (PMID 28604559, 2017). "It is possible that the 8-year follow-up period (waves 2–6) in our study was too short to capture changes in CRP concentration relevant to arthritis risk." (PMID 28604559, 2017). "In analysis using data from waves 1 to 4 only, direct pathways from CASP-19 and CRP intercepts to arthritis risk were attenuated but remained significant as did the association between CASP-19 and CRP intercept." (PMID 28604559, 2017). "The significant pathway between well-being at wave 1, CRP concentration at wave 2, and arthritis risk suggests that inflammatory processes are implicated in the link between well-being and arthritis risk." (PMID 28604559, 2017). "The indirect effect of CASP-19 intercept on arthritis risk via CRP intercept remained significant with a unit increase in CASP associated with a 0.002% (p = .020) reduction in arthritis risk." (PMID 28604559, 2017). "CRP accounts for a small proportion of the association between well-being and a reduced risk of arthritis." (PMID 28604559, 2017). "A 1% increase in CRP concentration at wave 2 was associated with an average of 0.002% (HR = 1.002, 95% CI = 1.001 to 0.002, p < .001) increase in arthritis risk." (PMID 28604559, 2017). "Next, we found that FTS, MTX, and FTS as an add-on to MTX treatments equally and significantly reduced the arthritis-associated upregulation of serum CRP levels at day 14 of the experiments." (PMID 28736556, 2017). "Mediation analysis revealed that the indirect effect of well-being (at wave 1) on arthritis risk via CRP (at wave 2) was significant (hazard ratio = 0.996, 95% confidence interval = 0.995 to 0.998, p < .001)." (PMID 28604559, 2017). "BAIAP2L1 (7q21.3) encodes a protein important in cytoskeleton organization that has been associated with the inflammatory marker CRP in patients with arthritis." (PMID 22829776, 2012). "Especially, all 7 of 7 responders with GI disorder displayed the improvment of GI disorders, which was associated with improvement of arthritis and biological markers such as CRP and ESR." (PMID 21208453, 2011). "It is therefore of interest that anti-interleukin-6 receptor antibody has been shown to be clinically beneficial for the treatment of arthritis and Crohn's disease and its action is associated with the suppression of C-reactive protein." (PMID 15570310, 2004).